PLK1 (polo like kinase 1)
Diseases named in the same sentence as PLK1 in open-access papers (continued):
Sharing a sentence is not in itself a finding about the gene and the disease.
cancer (continued). "To explore the possibility of combining both therapies, we analyzed the associations between PLK1 expression and tumor immunity in various different cancer types." (PMID 30631355, 2018). "The GDSC data analysis showed that high PLK1 expression levels were associated with decreased Treg cell enrichment levels in cancer cell lines (Spearman correlation, R=-0.13, P=3.29∗10−5)." (PMID 30631355, 2018). "Mitotic genes are rarely mutated in cancer, but rather affected by CNAs; for example amplification of PLK1, Aurora‐A, survivin, cyclin B, and NEK2." (PMID 30108112, 2018). "Early observations that linked PLK1 expression with cancer were from studies showing increased PLK1 expression in primary neoplastic tissues." (PMID 29899826, 2018). "Depleting PLK1 expression by RNA interference has been shown to specifically reduce cellular growth, induce mitotic arrest and strongly induce apoptosis in cancer cells including NSCLC cells, in particular when Ras mutated." (PMID 29983892, 2018). "Gene set enrichment analysis (GSEA) indicated that PLK1 is associated with various cancer-related pathways." (PMID 29190933, 2017). "The inhibition of PLK1 has been shown to cause cell cycle arrest at the G2/M phase and to increase apoptosis in cancer cells." (PMID 29186071, 2017). "PLK1 encodes a protein with multiple functions in the regulation of the cell cycle and is a known target gene for cancer treatment, and druggable with several small molecule inhibitors currently tested in clinical trials." (PMID 29228663, 2017). "The overexpression of PLK1 has been linked to decreased survival rate and poor prognosis in various cancer types." (PMID 29186071, 2017). "In this regard, PLK1 can serve as a molecular biomarker to improve the stratification of cancer patients at high-, intermediate-, or low-risk of metastatic progression." (PMID 28953239, 2017). "Inhibition of Plk1 activity causes mitotic arrest and apoptotic cell death in most cancer cell lines." (PMID 27902479, 2017). "The major problems commonly associated with currently available PLK1 inhibitors are insufficient specificity and cancer cell-selective killing." (PMID 28953239, 2017). "As hyper-activation of PLK-1 is broadly associated with poor prognosis and cancer progression, it is one of the most extensively studied mitotic kinases." (PMID 28415805, 2017). "PLK1 inhibition has been reported to cause mitotic arrest and initiate apoptosis in various human cancer cell lines." (PMID 26046302, 2016). "For instance, Polo-like kinase 1 (PLK1) and E2F-mediated associated pathways were implicated in cancer recurrence and metastasis." (PMID 27647437, 2016). "PLK1 is implicated in the regulation of mitotic machinery and is overexpressed in many cancer cells." (PMID 26978377, 2016). "PLK1 is overexpressed in a variety of human cancers, and overexpression is linked to chromosomal instability and aneuploidy." (PMID 27538997, 2016). "This strategy was best suited to support our aim, which was to use PLK1 overexpression as the vulnerability associated with cancer cells and to test if these PLK1-overexpressing, heterogeneous population of cells exhibit SDL with PP2A inhibition." (PMID 27557495, 2016).
cancer (continued). "Extensive volume of literature cites the association of PLK1 with G2-M transition and mitosis in numerous cancer conditions." (PMID 26820885, 2016). "Overexpression of Plk1 has been observed in multiple human cancers and has been associated with poor prognosis." (PMID 25794535, 2015). "A growing body of evidence suggests that Plk1 overexpression is tightly associated with the development of human cancers." (PMID 26500787, 2015). "Correlated with the loss of functional tumor suppressors, transcriptional deregulation of Plk1 is reported in various cancers and associated with CIN and oncogenic transformation." (PMID 25999914, 2015). "Overexpression is associated with poor prognosis in several cancer entities, whereby expression of PLK1 shows high inter-individual variability." (PMID 24767679, 2014). "Overexpression of PLK1 has been found in the genetic profile of several different human cancers, and has been linked with poor prognosis." (PMID 23658603, 2013). "Using Cytoscape tool; subnetworks were constructed for G1, S, G2/M, cytokinesis and checkpoints with cancer association to investigate the additional functions of Plk1." (PMID 23967120, 2013). "Our results uncover a role of Plk1 in linking DNA damage recognition with HR repair and suggest a molecular mechanism for cancer development associated with elevated activity of Plk1." (PMID 22325354, 2012). "PLK1 is overexpressed in a range of human tumors, and PLK1 overexpression is associated with a bad cancer prognosis." (PMID 22649730, 2012). "Its subcellular localisation and protein stability are regulated by several crucial mitotic kinases, such as Plk1, Nek2, Cdc2 and Aurora B. Several lines of evidence have linked Nlp to human cancer." (PMID 21505454, 2011). "PLK-1 is overexpressed in many types of malignancies and its overexpression is associated with poor prognosis of cancer patients." (PMID 21884621, 2011). "A corresponding cdc5-ad mutation in Plks has not yet been isolated in mammals; however, it was found that Plk1 depletion severely blocks checkpoint recovery and adaptation, and rapidly causes cell death in cancer cells." (PMID 20098491, 2010). "Several missense mutations of Plk1 have been identified in different cancer cell lines with various tissue origins." (PMID 19161615, 2009). "The immunosuppressive TME observed in PLK1-high tumors likely results from complex interactions between tumor cells, immune cells, and chemokine networks, a recognized hallmark of cancer immunotherapy response (Nagarsheth, Wicha & Zou, 2017; Hegde & Chen, 2020)." (PMID 41556056, 2026). "It suggests that PLK1 is an underlying therapeutic target for chemotherapy-resistant cancer." (PMID 40665355, 2025). "As with KRAS mutations, cancers with higher PLK1 expression levels have lower immune activity." (PMID 40615690, 2025). "In reverse, the inhibition of PLK1 could cause mitotic blockage and apoptosis in most cancers [17b]." (PMID 41476654, 2025). "The molecular mechanism and overview of predicted PLK1 cancer mutations were analyzed by MutPred2." (PMID 41404416, 2025). "PLK1 is a serine/threonine kinase that governs centrosome maturation, spindle assembly, and G2/M transition, and its suppression is associated with cell cycle arrest and mitotic catastrophe in cancer cells." (PMID 40508126, 2025). "Polo Like Kinase 1 (PLK1), a key regulator of mitosis whose overexpression is often associated with poor survival rates in cancer, continues to be widely investigated as an oncology drug target with clinical trials evaluating second and third generation inhibitors." (PMID 40379873, 2025).
cancer (continued). "Both AURKA and PLK1 are serine/threonine-protein kinases, have been implicated in gliomagenesis, and are potential drug targets (with ongoing clinical trials) for many different cancers." (PMID 39565278, 2025). "Targeting PLK1 disrupts spindle assembly, causing mitotic arrest and cancer cell death." (PMID 40081286, 2025). "A variety of pathophysiological mechanisms could underlie the association between PLK-1 and cancer progression." (PMID 39857637, 2024). "In human PDACs, the simultaneous detection of loss of Plk3 expression and overexpression of Plk1 might disrupt the regulation of anoikis, subsequently fueling cancer progression and metastasis." (PMID 38605037, 2024). "Furthermore, PLK1 negatively regulates MHC-II expression in cancer cells, which has been shown to be associated with compromised tumor immunity and unfavorable patient outcomes." (PMID 38885192, 2024). "Additionally, PLK1 is closely associated with immunotherapy, chemotherapy, and radiotherapy for cancer." (PMID 39596658, 2024). "PLK1 is overexpressed in many cancers and is associated with poor outcomes." (PMID 39513002, 2024). "Besides, the regulation of MHC-II can be extended to cancer cells, where high PLK1 is also associated with low MHC-II expression." (PMID 38885192, 2024). "Moreover, extensive studies have revealed that PLK1 was overexpressed in a variety of human cancers and associated with poor prognoses in multiple types of human cancers." (PMID 38495493, 2024). "Furthermore, overexpression of PLK-1 has been identified in various types of cancer, including CRC, and is associated with tumor size, depth of invasion, lymph node involvement, and poorer survival outcomes." (PMID 39857637, 2024). "In addition, PLK1 overexpression has been associated with chemotherapy resistance, and PLK1 inhibition can increase the cancer cell sensitivity to chemotherapy and radiation." (PMID 36597205, 2023). "Polo-like kinase 1 (Plk1) is a mitotic serine/threonine (S/T) kinase, whose overexpression is closely associated with aggressiveness and poor prognosis for a wide spectrum of human cancers." (PMID 37603740, 2023). "Poor prognosis in cancer is often associated with PLK1 overexpression." (PMID 38067203, 2023). "In addition, we discovered that the most abundant mutation type of PLK1 was “missense mutation” in pan-cancer." (PMID 36618405, 2022). "PLK1 is found overexpressed in most cancers and is associated with a poor prognosis." (PMID 35983074, 2022). "However, it is currently unclear why overexpression of PLK1 causes cancer or is a consequence of the overproliferation of cancer cells." (PMID 35563642, 2022). "PLK1 regulates the cell cycle, and cell cycle dysregulation is the primary cause of cancer." (PMID 36297281, 2022). "PLK1 mutation is strongly associated with the emergence and progression of malignant tumors and is considered as one of the most promising targets for targeted anti-cancer therapy." (PMID 35114891, 2022). "Overexpression of PLK1 in cancer cells is also associated with poor prognoses." (PMID 35563642, 2022). "Moreover, overexpression of PLK1 was associated with poor prognosis of many cancers, making PLK1 an attractive target for cancer treatment." (PMID 36355508, 2022). "PLK1 is linked with proliferation of cancer cells, but this might be gene is liable for proliferation of pituitary prolactinoma." (PMID 33709028, 2021). "Given its central role in mitosis, the AURKA/PLK1 axis is associated with many types of cancers." (PMID 34500603, 2021). "PLK1 inhibition caused monopolar spindles and mitotic catastrophe in (pre)cancer cells." (PMID 34071997, 2021).
cancer (continued). "In cancer invasion, PLK1 is also associated with phosphorylation of vimentin at Ser83, which regulates cell surface β1-integrin, though its regulatory mechanism in metastasis remains unclear." (PMID 33963314, 2021). "Reduced PLK1 levels have been linked to tumorigenesis in Plk1-heterozygous mice, though in other PLK1-reduced settings a cancer-promoting effect of low and drastically reduced PLK1 could not be detected." (PMID 34065956, 2021). "Dysregulation of PLK1 is a hallmark of a multitude of cancers." (PMID 34065956, 2021). "High PLK1 expression levels in many cancers including GBM are associated with poor outcomes." (PMID 34680264, 2021). "PLK1 overexpression occurs in various cancers and is often associated with a poor prognosis." (PMID 34093198, 2021). "Research has been shown that cancer cells with KRAS mutation are more sensitive to PLK1 inhibitors than KRAS wild-type cancers, suggesting that KRAS mutation induces mitotic stress in tumor cells and may underlie tumor sensitivity to anti-mitotic agents." (PMID 32486290, 2020). "Moreover, it has been found that PLK1 was associated with drug resistance of several cancer chemotherapy drugs." (PMID 33106477, 2020). "PLK1 overexpression was reported to be associated with poor prognoses in a variety of cancers." (PMID 33352742, 2020). "While it was reported that KRAS mutant cancer cells are highly sensitive to PLK1 inhibitors, detailed mechanisms underlying the sensitivity are largely unknown." (PMID 32486290, 2020). "Genistein was proposed as a Plk1 inhibitor, which effectively downregulates the expression of multidrug resistance protein 1 and multidrug resistance-associated protein 1, key factors inducing chemoresistance in paclitaxel-resistant cancer cells." (PMID 31866857, 2019). "Together, these data suggest that a combination of low RIPK1 and high PLK1 might be associated with chromosomal mis-segregation and long-term aneuploidy in human cancers." (PMID 30598363, 2019). "Additionally, in parental cells, genes associated with cell division, Aurora B pathway, PLK1 pathway, DNA replication, and pathways in cancer are downregulated by CB-5083." (PMID 31358864, 2019). "Thus, PLK1 inhibition by various agents can cause postmitotic DNA damage and senescence in several cancer cell lines." (PMID 31159515, 2019). "PLK1 overexpression is oncogenic and is associated with poor prognosis in various cancers." (PMID 30631355, 2018). "Moreover, we analyzed the associations of the drug sensitivities of PLK1 inhibitors with tumor immunity in cancer cell lines." (PMID 30631355, 2018). "Interestingly, some of these genes are known to be over-expressed in cancer or associated with poor prognosis such as PLK1, ANLN and FBXO530–32." (PMID 29777112, 2018). "Furthermore, the GDSC data analysis showed that the PLK1 expression levels were positively associated with the CTA enrichment levels in cancer cell lines (Spearman correlation, R=0.22, P=4.09∗10−12)." (PMID 30631355, 2018). "Furthermore, we associated the PLK1 expression levels with the enrichment levels of TILs in cancers." (PMID 30631355, 2018).
cancer (continued). "PLK1 is a mitotic regulator overexpressed in cancer; however, whether this overexpression causally contributes to tumor development is unclear." (PMID 30069007, 2018). "Indeed, Optn specifically controls the activity of a mitotic enzyme, Polo-like kinase 1 (PLK1) that has been linked to the development of several types of cancer when its activity is deregulated." (PMID 29971063, 2018). "However, the stabilization of BEX4 by the constitutive expression of PLK1 resulted in severe mitotic defects, which are associated with cancer." (PMID 30367032, 2018). "We analyzed the associations of PLK1 expression with tumor immunity in 33 different cancer types." (PMID 30631355, 2018). "Overexpressed PLK-1 causes cancer in epithelial cells of lower genital tract." (PMID 28415805, 2017). "Indeed, PLK1 has been reported to be closely associated with drug resistance in cancer cells to a number of chemotherapy drugs, including doxorubicin, paclitaxel, and gemcitabine." (PMID 28953239, 2017). "However, recent studies show that PLK1 is capable of contributing to carcinogenesis through interconnections with multiple cancer-associated pathways." (PMID 28953239, 2017). "Loss of PLK1 expression can induce pro-apoptotic pathways and inhibit growth in cancer cells." (PMID 34322587, 2017). "PLK1 has previously been implicated in several adult and pediatric cancers including CNS tumors." (PMID 29228610, 2017). "Increasing evidence suggests that PLK1 is closely linked to human cancer development." (PMID 28953239, 2017). "Based on these findings, PLK1 has been proposed as a novel diagnostic marker for cancer, and its inhibition might represent a rewarding approach in cancer therapy." (PMID 26799423, 2016). "However, our study is the first to demonstrate the causal role of PLK1 in regulating cancer cell motility." (PMID 27003818, 2016). "Since increased PLK-1 expression has been correlated to poor prognosis and aggressiveness of cancers, we evaluated whether a similar association exists in ACC." (PMID 26754547, 2016). "As a lot of evidence suggested the human Pole homologue PLK1 plays important role in tumorigenesis, there was still debate to whether overexpression PLK1 in some cancer is the consequence or the cause of cancer." (PMID 26090465, 2015). "Inhibition of polo like kinase (Plk) 1 causes growth inhibition in various cancers." (PMID 26807203, 2015). "Importantly, we provide evidence for co-upregulation of FOXM1 and PLK1 expression in these cancers as predicted from their co-regulatory association." (PMID 26576650, 2015). "Such polymorphisms could be useful to investigate whether PLK1 alters the risk for and the course of cancer and they could have an impact on the response to PLK1 inhibitors." (PMID 24767679, 2014). "PLK1 polymorphisms could be useful with regard to risk as well as outcome studies in Caucasian cancer patients but also in other ethnicities because, according to dbSNP data, rs27770 occurs in other ethnicities as well." (PMID 24767679, 2014). "Importantly, increased activity of Plk1 is closely linked to malignancy, and Plk1 inhibition sensitizes cancer cells to DNA damage treatment." (PMID 22325354, 2012). "PLK-1 has also been demonstrated to be associated with cancer invasion and metastasis." (PMID 19775446, 2009). "The association of Plk1 overexpression with cancers could be explained as a result of high mitotic index of tumor cells since Plk1 levels are cell cycle-regulated with a peak during mitosis." (PMID 19161615, 2009).